SNORA70I (small nucleolar RNA, H/ACA box 70I)
Gene: Small nucleolar RNA gene on chromosome 2 (214,846,947 to 214,847,081, forward strand). Ensembl gene ENSG00000207274.
Gene Ontology:
Biological process: RNA processing
Cellular component: nucleolus
Homologues: Orthologues: chimpanzee SNORA70 (99% identical). Paralogues in human: SNORA70 (94% identical), SNORA70G (92% identical), SNORA70H (92% identical), SNORA70B (90% identical), SNORA70C (90% identical), SNORA70J (90% identical), SNORA70D (90% identical), SNORA70 (89% identical), SNORA70 (87% identical), SNORA70E (86% identical), SNORA70F (86% identical), SNORA70 (85% identical), and 14 more.